IFNG (interferon gamma)
Diseases named in the same sentence as IFNG in open-access papers (continued):
Sharing a sentence is not in itself a finding about the gene and the disease.
cancer (continued). "Previous in vitro study on epithelial cancer cells has shown that cancer cell lines of different origins—when incubated with either supernatant derived from a mixed lymphocyte population or a mix of inflammatory cytokines (TNFα, TGFβ and IFNγ)—undergo a series of changes typical of the EMT." (PMID 35096592, 2021). "Next, we analyzed the relationships of LCK with IFNG, CCL5, and CXCR3, using TCGA bulk RNA-sequencing data, and we found significant associations in the expression levels of LCK with IFNG (total rho=0.73), CCL5 (total rho=0.80), and CXCR3 (total rho=0.84) in most cancer types." (PMID 35069521, 2021). "The release of excess lactate/H+ by cancer cells into the extracellular medium actually makes the concentration gradients of these waste products less favorable for T cells to maintain glycolysis, thereby directly impacting on interferon gamma (IFN-γ) and cytokine production." (PMID 32438640, 2020). "To investigate the molecular mechanism(s) underpinning the atrophying activity of muscular RAGE in cancer condition, we used two well‐characterized in vitro models of muscle atrophy consisting of myotube cultures exposed to TNFα alone or in combination with IFNγ." (PMID 32159297, 2020). "The anti-inflammatory potential of probiotics can counteract cancer development under various discrete pathways, such as increased secretion of immunoglobulin A (IgA) levels, regulation of cyclooxygenase-2, and modulation of nuclear factor kappa B (NF-kB) and interferon-gamma (IFN-γ)." (PMID 33042069, 2020). "However, IFNγ may also upregulate PD-L1 expression on cancer cells to escape T cell-mediated immune response." (PMID 31640814, 2019). "Multiple other recombinant cytokines have already been approved for treatment of patients; IL-2 for cancer, several IFNα derivatives for cancer and viral infections, IL-11 thrombocytopenia induced by chemotherapy, IFNβ for multiple sclerosis and IFNγ for osteoporosis and cancer." (PMID 30622524, 2018). "Likewise, IFNγ can also have a dramatic effect in cancer immunology." (PMID 30026743, 2018). "However, its expression can be induced by some cancer drivers or by IFNγ." (PMID 30409126, 2018). "Thus, the outcome of IFNγ cancer therapy may depend on the cellular, microenvironmental, and molecular contexts." (PMID 28526810, 2017). "Several counterarguments against the cancer immunosurveillance theories were discarded with the exploitation of mice models deficient in adaptive immunity (RAG2 knockout mice) or mice lacking components of interferon-gamma (IFN-γ) signaling cascade." (PMID 28116316, 2016). "Moreover, the AV-SLP conjugates could induce a specific IFNγ+ response in three out of six LN cell cultures derived from randomly selected HPV16+ cancer patients whereas free SLPs were able to do so in one out of six cultures." (PMID 27564262, 2016). "Furthermore, promising new treatment paradigms for these cancers may involve the addition of anti-PD1 or anti-CD137 immunotherapies to stimulate IFNγ-producing CD8+ T cells and maximize benefits from Her2 inhibitors such as trastuzumab or other therapies." (PMID 26395345, 2015). "Furthermore, as cited above, the presence of IFNγ-producing Th17 cells could have beneficial protective roles in infections and cancer." (PMID 26101460, 2015). "In cancers with chronic virus infection, the anti-cancer and/or antiviral immune response could induce the secretion of important inflammatory factors like interferon gamma (IFN-γ), which may be utilized by cancer cell itself to maintain immune suppressive milieu." (PMID 26361045, 2015). "This truncated peptide induced similar levels of IFNγ in NK cells compared with that using the full-length lunasin, suggesting the last 11 amino acids are not required for lunasin’s immune modulatory function in NK cells although they are critical for inducing apoptosis in transformed cancer cells." (PMID 24363024, 2014).
cancer (continued). "Because interferon-gamma, opioids and hypoxia are part of the host response and the therapeutic regiments administered to cancer patients, the conditions that accompany cancer may also provide the signals for P. aeruginosa virulence induction." (PMID 24432250, 2014). "However, the existence of high interferon-gamma (IFN-γ) expression secreted by NK cells or immune cells in CRC patients remains controversial because NK cell cytotoxicity is traditionally believed to control immunosurveillance over cancer and atypical cells." (PMID 22496728, 2012). "Our results demonstrate that Tex markers are consistently expressed at varying levels, while the effector genes (IFNG, GZMB, and PRF1) show lower expression levels across most cancer types." (PMID 40076932, 2025). "Consistent with previous reports, treatment with IFNγ significantly induced PD-L1 expression in MC38 and CT26 cancer cells." (PMID 41155994, 2025). "Anti-cancer efficacy was further promoted by the repression of transforming growth factor-beta (TGF-β) and STAT3, and the elevated expression of TNFα, IFNγ, and CXCR4." (PMID 39946032, 2025). "We found that in both individual cancer and pan-cancer cohorts, UBA1 expression was significantly negatively correlated with the expression of IFNG or CD8+ T-cell–related signatures." (PMID 39540840, 2025). "As indicated by the release of granzyme B (GrB) and interferon gamma (IFNγ), co-culture of αPD-L1-γδ T cells with OVCAR-8 cancer cells induced T cell activation." (PMID 40842867, 2025). "XmAb808 promoted IFNγ release from T cells and IL2-mediated expansion of T cells with enhanced survival, translating to increased T cell–mediated killing of cancer cells in vitro but only in the presence of both Signal 1 and B7-H3+ target cells." (PMID 39301613, 2025). "4T1 cells were infected with SFV/Luc encoding firefly Luc gene (referred to as SFV or Luc) and two potential immunotherapy virus vectors, SFV/IFNγ and SFV/TNFα, to investigate the possibility of mitigating cancer cell effects on macrophages." (PMID 40547518, 2025). "In particular, it is expressed in interferon gamma (IFN-γ) activated T cells and is important in T cell dysfunction in cancer." (PMID 40645187, 2025). "Multiple studies support that miR-146a influences the expression of genes involved in cancer progression and metastasis by modulating key signaling pathways, including TNFα/TRAF6, IFNγ/STAT, GPCR, PI3K-AKT-mTOR, and TGFβ/SMAD." (PMID 40277937, 2025). "To identify novel pathways and drugs that regulate the IFNγ-dependent PD-L1, we expressed GFP under the control of mouse PD-L1 promoter in mouse cancer cells that up regulate PD-L1 and CXCL10 in response to IFNγ stimulation." (PMID 40264756, 2025). "The JAK-STAT3 pathway, predominantly activated by cytokines such as IL-6, IFNγ, LIF, and OSM, plays a central role in cancer cachexia pathogenesis." (PMID 40704145, 2025). "On top of that, SFV/IFNγ treatment upregulates the expression of macrophage MHC II genes (H2-Ab1) and therefore can activate an adaptive immune response against cancer." (PMID 40547518, 2025). "NK cells cocultured with the indicated cancer cells were collected and subjected to flow cytometry to analyze the proportions of CD56-, IFNγ-, and granzyme B (GZMB)-positive NK cells." (PMID 39402211, 2025). "Interferon-gamma (IFN-γ), a pro-inflammatory cytokine mainly secreted by T cells and natural killer (NK) cells, plays a pivotal role in cancer cachexia by triggering the JAK-STAT signaling pathway in muscle cells." (PMID 40869331, 2025). "IL-12 is known to promote IFNγ production in T cells, APC licensing and ultimately CD8+ T cell cytotoxic activity against cancer cells." (PMID 40216735, 2025). "Enhanced T cell activity promotes cancer cell death through effector mechanisms involving perforin (PFN), granzyme B (GzmB), interferon-gamma (IFNγ), and tumor necrosis factor-alpha (TNFα)." (PMID 40806510, 2025).
cancer (continued). "It modulates the production of cytokines, such as interferon-gamma (IFN-γ), which helps in stimulating the immune response against cancer cells." (PMID 39861761, 2025). "AM52.1CAR T cells produced pro-inflammatory cytokines, including macrophage inflammatory protein 1 beta (MIP-1β), interleukin (IL-8), interferon gamma (IFN-γ), tumor necrosis factor alpha (TNF-α), and IL-13, in response to STn-positive cancer cells." (PMID 40925376, 2025). "Interferon gamma stimulates CXCL9 production by monocytes, endothelial cells, fibroblasts and cancer cells leading to increased chemotaxis and infiltration of the TME." (PMID 39080202, 2024). "In tumors where PD-L1 is reactively induced by IFNγ secreted by ACPs, FASN blockade, which disrupts the maturation of PD-L1 on the surface of cancer cells, can be used to overcome adaptive immune resistance." (PMID 39349429, 2024). "Early studies revealed numerous antitumor effects of IFNγ, including enhanced MHC expression and antigen presentation on cancer cells, increased T-cell cytotoxic activity, and increased cancer cell cycle arrest and apoptosis." (PMID 39123403, 2024). "A thorough investigation of links between autophagy, IFNγ, and CITA/NLRC5 is necessary to further elucidate the complex interactions between autophagy and antigen presentation in cancer." (PMID 39409895, 2024). "Adding to the complexity, interferon-gamma (IFNG/IFN-γ), which is released from CD8+ T cells, downregulates the expression of SLC7A11, effectively promoting ferroptosis induction in HT-1080 and B16 cancer cells." (PMID 39090114, 2024). "HP1β inhibition suppressed IFNγ-induced STAT1 activation, which reduced PD-L1 expression and enhanced cancer cell killing by CAR T-cells." (PMID 39519018, 2024). "Intriguingly, IFNγ also suppresses SLC7A11-mediated cystine transport in macrophages, indicating that IFNγ can regulate SLC7A11 in both cancer and non-cancer contexts." (PMID 38322268, 2024). "Cytotoxic CD8+ T cells secrete interferonγ (IFNγ), which inhibits SLC7A11 by activating the JAK/STAT1 pathway in cancer cells, thereby inducing ferroptosis in cancer cells." (PMID 39238647, 2024). "IFNγ secretion triggers the expression of indoleamine 2, 3-dioxygenase 1 (IDO1) in cancer cells, an enzyme that catabolizes Trp to generate metabolites that induce effector T cell dysfunction." (PMID 39154912, 2024). "Nevertheless, a link has been recently identified between a subclass of HERVs and the ability to trigger pathologic innate immune signaling in cancer involving STING and IFNγ, with important implications for PD-L1 expression and cancer immunotherapy." (PMID 38338893, 2024). "Our data suggested a novel role of TPST2 in the regulation of cancer immunity, in which TPST2-mediated tyrosine sulfation of IFNGR1 at Y397 constrained IFNγ signaling." (PMID 39095793, 2024). "In TCGA-BRCA database, DCTPP1, SLC27A2, and IFNG were highly expressed in cancer tissues, while MYH3 was expressed at a low level in cancer tissues." (PMID 38753091, 2024). "CD8+ T cells can specifically detect and eliminate cancer cells by secreting effector cytokines (tumor necrosis factor (TNF) and interferon-γ (IFNγ)) or cytotoxic molecules (such as perforin and granzymes)." (PMID 39074262, 2024). "We confirmed that IMC-F106C recognized PRAME-pHLA on the cancer cell surface, redirected donor T cells, and efficiently mounted an anti-PRAME-specific antitumor response (i.e. CD8+ IFNγ release and cytolysis)." (PMID 39659431, 2024). "Enrichment analysis indicated that T and B cell marker genes principally engaged in response to interferon-gamma (IFN-γ), which was indispensable to the cancer-killing of CAR-T cell therapy." (PMID 37889543, 2023). "In blood samples from healthy donors and from patients with cancer, AC484 increased IFNγ-induced STAT1 phosphorylation and CXCL10 production, which suggested that AC484-enhanced pathway engagement resulted in amplified downstream functional effects." (PMID 37794185, 2023).
cancer (continued). "The PANoptosis score was positively correlated with many malignant pathways in pan-cancer, especially IL6-JAK-STAT3 signaling, interferon-gamma response, inflammatory response, IL2-STAT5 signaling, and TNF-a signaling via NF-kB signaling." (PMID 36890219, 2023). "Hence, a more in-depth investigation into the function of cytokine-induced inflammation and cancer-associated muscle atrophy, with a particular focus on the participation of TNF-α, IL-1, IL-6, and IFNγ, could yield significant knowledge regarding the fundamental mechanisms involved." (PMID 37959329, 2023). "Contradictory to in vivo results that show an increase in PD-L1 expression in cancer cells, here they concluded that irradiation (IR) is augmenting CD8+ T cells immunity by suppressing PD-L1 expression in an IFNγ related manner." (PMID 37006319, 2023). "Although no much information is currently available on this taxon, R. lactatiformans was part of an 11-strain consortium that induced interferon gamma (IFNɣ+)-producing CD8+ T cells in mice, enhancing anti-cancer immunity." (PMID 36639555, 2023). "For example, the top 15 hub genes in T cells from all types of cancers included those involved in cell-mediated immunity (GZMB, PRF1 and IFNG) and immune checkpoint signaling pathways (TIGIT and CTLA4)." (PMID 36350625, 2023). "Th1 CD4+ T cells secrete cytokines such as IL2 and IFNγ, which promote effector T cell proliferation and induce MHC expression on the surface of cancer cells, respectively." (PMID 37830618, 2023). "In certain cancers that progress toward cachexia, the release of various cytokines, such as TNF-α, IL-6, and interferon gamma (IFN-γ), plays a significant role." (PMID 37755304, 2023). "Localsupplementation of IFNγ drove MHC-I and MHC-II expression in vitro, restoring the local antigen presentation thatwas otherwise downregulated by the cancer cells." (PMID 37797944, 2023). "Besides, though there have been several clinical trials examining the efficacy and safety of IFNγ as an onco-therapy along with other treatment modalities, no trial has been initiated to investigate the efficacy or safety of IFNγ as an anti-cancer therapy alone." (PMID 37671945, 2023). "Genome-wide CRISPR screens of a broad panel of mouse cancer cell lines, including B16F10 and MC38, have shown that that Ptpn2 and other negative regulators of the IFNγ response are involved in immune evasion by multiple cancer types." (PMID 36968224, 2023). "In cancer progression, CD226 was negatively regulated by TME-driven immune suppression, while IFNG and TIGIT were highly expressed in specific TILs." (PMID 37056782, 2023). "It is well known that cytotoxic T cells depend on interferon gamma (IFN-γ) and granzyme B to attack cancer cells." (PMID 36816023, 2023). "To explore the possibility of lower baseline IFNG gene expression in normal brain versus other anatomic sites, we analyzed the GENT2 database of normal and cancer gene expression." (PMID 37964004, 2023). "Exposure to cell-free ascites supernatants from HGSOC patients drastically suppressed TAGLN2, IFNG, and GZMB expression in pre-activated CD8+ T cells obtained from peripheral blood of cancer-free women." (PMID 38168227, 2023). "In most cancer entities, including CRC, the inflammatory cytokine interferon-gamma (IFN-γ), secreted by cytotoxic T cells, NK cells, γδ T cells and Th1 cells, is also associated with prolonged survival." (PMID 37511431, 2023). "These include TNF-α, interleukins (IL-6; IL-1β and IL-1α), interferon-gamma (IFN-γ), leukemia inhibitory factor (LIF), and the TGF-β superfamily have been shown to mediate cancer-induced muscle wasting." (PMID 38203683, 2023). "During the early phases of cancer, activated immune cells (NKs, CD8+, CD4+ T cells) secrete IFNγ, thereby modulating the activity of macrophages, DCs, Th1 CD4+helper T cells, and B cells to eliminate cancer cells." (PMID 37190141, 2023).
cancer (continued). "This is further recapitulated in ingenuity pathway analysis (IPA), as enriched terms to psPD represent several immune response pathways driven by TREM1, TNF, IFNG, IL1, and IL6 while PD was primarily demarcated by E2F-mediated cancer activity." (PMID 38049893, 2023). "The finding of significantly higher IFNG RNA expression in unstable MSI, high TMB, and high PD-L1 expression is compatible with previous reports and adds a pan-cancer landscape." (PMID 37553332, 2023). "In cancers, MHC-I expression is mainly induced by the type II interferon, IFNγ, which is secreted primarily by T cells and natural killer (NK) cells and signals through the JAK–STAT pathway." (PMID 37450351, 2023). "Based on these observations, we wondered whether it is possible to trigger IFNγ-independent expression of HLA-I in cancer cells by using available drugs, which could potentially improve the efficacy of ICI therapies in tumors that have mutations that render them insensitive to IFNγ." (PMID 36743451, 2023). "We have developed an immunoPET tracer utilizing a radiolabeled antibody to IFNγ to monitor response to cancer immunotherapy, and we previously demonstrated that anti-IFNγ PET can identify HER2 cancer vaccine-induced intratumoral immune activation." (PMID 38130991, 2023). "Interestingly, recent works have revealed the existence of an IFNγ-independent mechanism that promotes HLA-I expression through activation of the innate immune system, although the relevance of this pathway to modulate HLA-I expression in cancer immunotherapy remains to be fully ascertained." (PMID 36743451, 2023). "Activation of the FGFR signaling inhibits IFNγ-induced STAT1 phosphorylation and the expression of PD-L1, thus protecting cancer cells from the cytotoxic effects of CD8+ T cells, thereby supporting resistance to anti-cancer therapies." (PMID 37190141, 2023). "In situ hybridization analysis showed high IFNγ expression in cancer samples and IMC analysis of gastric biopsies revealed a strong immune cell infiltration (> 50%) suggesting that the main source of IFNγ was the immune infiltrate." (PMID 36598557, 2023). "Genetic deletion of EP2 and EP4 receptors for PGE2 facilitates the early intra-tumoral accumulation of interferon gamma (IFN-γ)-producing NK cells and an IFN-γ-dependent re-education of the TME against cancer." (PMID 37298470, 2023). "ZNF683+ Trm cells, identified as cancer-specific Trm cells in this study, have higher IFNG and GZMB expression compared with ZNF683– Trm cells, suggesting that cancer-specific Trm cells have high cytotoxic potential." (PMID 36869093, 2023). "TET2 can mediate the interferon gamma (IFNγ)-JAK-STAT signaling pathway to control chemokine and PD-L1 expression, lymphocyte infiltration, and cancer immunity." (PMID 37488178, 2023). "Kynurenine engenders an immunosuppressive environment by promoting Treg development and decreasing the viability and IFNγ expression of CD8+ T cells, while also directly increasing cancer cell proliferation." (PMID 37936700, 2023). "The IFNγ activates the JAK/STAT pathways, including in cancer cells, with consecutive transcription of PD-L1 and other inhibitory ligands." (PMID 35806366, 2022). "According to our findings, NMNGs in pan-cancer were significantly correlated with a number of signaling pathways, including TNFA signaling via NFKB, KRAS signaling, interferon-gamma response, inflammatory response, and epithelial-mesenchymal transition (EMT)." (PMID 36726460, 2022). "The samples from the T-LGLL group were enriched to the high-IFNγ group (P < 0.05, Fisher’s one-sided exact test), confirming that IFNγ response is more strongly activated in T-LGLL than in other cancers." (PMID 35411050, 2022). "All these results describe the scenarios that the extrinsic IFNγ stimulation and the intrinsic JAK/STAT signaling pathway are involved in the up-regulation of PD-L1 expression in cancer cells." (PMID 35107757, 2022).